FOXM1 (forkhead box M1)
Diseases named in the same sentence as FOXM1 in open-access papers (continued):
Sharing a sentence is not in itself a finding about the gene and the disease.
cancer (continued). "The phosphorylated FoxM1 at Ser25 by PLK1 acquires the reprogramming ability to stimulate the invasive traits in cancer and influence immune cell plasticity." (PMID 37968723, 2023). "Early studies revealed that a cell-penetrating ARF inhibitory peptide effectively blocked FOXM1 activity in cultured cancer cells and mice, but the pharmacokinetics of such peptides are not suitable for clinical use." (PMID 37686402, 2023). "Conditional knockout of FOXM1 inhibits cancer development in multiple mouse organs, such as the liver, lung, and rectum." (PMID 37598210, 2023). "Increased FOXM1 expression is critical for reducing ROS levels in proliferating cells thereby controlling ROS mediated oxidative DNA damage in cancer cells." (PMID 37025658, 2023). "FOXM1 is also involved in promoting metastasis and invasion of cancer cells and maintaining the characteristics of cancer stem cells." (PMID 37344857, 2023). "FOXM1 is a predominant modulator of cancer growth and metastasis that is selectively expressed in dividing cells." (PMID 37626655, 2023). "Due to this variety of targets for controlling FOXM1 expression, its inhibition seems to be a promising strategy in cancer." (PMID 37821870, 2023). "When we analysed the cancer-specific genes like Cdc20, Hmmr, Tpx2, Cenpf, Birc5, Ube2c, Foxm1,Pold4, Nup210, Cenpm and Orc1, these pro-carcinogenic genes found to be over expressed in the disease control group." (PMID 36650455, 2023). "Second, dysregulated transcription factors in cancer, such as FOXM1, orchestrate impactful alterations in gene expression programs and biological processes, which drive tumor pathogenesis." (PMID 37686402, 2023). "circTP63 induces cancer progression via upregulating FOXM1 production by sponging miR-873-3p, which is an inhibitor of FOXM1 mRNA translation." (PMID 36380816, 2023). "Among the 19 drugs identified by both the CMAP query and the DART algorithm as repressing the FOXM1 pathway, some have been noted in other studies for their potential to treat cancer." (PMID 36424525, 2023). "On the one hand, FOXM1 promotes cancer development by transactivating the expression of its target genes during transcription." (PMID 37234166, 2023). "To date, the only therapies directed at FOXM1 have been a few cancer vaccines, which include FOXM1 peptides." (PMID 37174744, 2023). "The result displayed that FOXM1 mRNA was clearly upregulated in most kinds of cancers, indicating the vital functions of FOXM1 on the occurrence and progression of tumors." (PMID 37159818, 2023). "A FOXM1 DBD-specific single-strand DNA aptamer has also been selected to inhibit FOXM1 transcriptional functions in cancer cells." (PMID 37598210, 2023). "There is broad interest in targeting FOXM1 in cancer therapy, and we prioritized three reasons for doing so in MPNST." (PMID 37686402, 2023). "The FOXM1 transcription factor has multiple roles in cancer progression and metastasis, including promoting cell proliferation, self-renewal, migration, invasion, angiogenesis, and EMT." (PMID 37835395, 2023). "Transcription factor FOXM1 overexpresses in multiple cancers and is considered an effective target for cancer therapeutic drug development." (PMID 37598210, 2023). "FOXM1 is upregulated in several cancers including lung, renal cell, ovarian, breast, and colorectal cancers." (PMID 38001498, 2023). "The expression of certain cell cycle genes (CCNB1, CCNE1, CCNE2, and FOXM1) was race-dependent in several cancer types and correlated with significant survival differences." (PMID 37345032, 2023). "We confirmed that M1-21 inhibited the functions of both FOXM1 and β-catenin, thereby inhibiting cancer cells across multiple aspects of phenotypes." (PMID 37344857, 2023). "In multiple cancers, FOXM1 is upregulated and its levels in clinical cancer samples can predict disease diagnosis and prognosis." (PMID 37598210, 2023).
cancer (continued). "Increased expression of FOXM1 is observed in a variety of cancer types, and elevated expression has been related to poor overall survival." (PMID 37622176, 2023). "IQ-domain GTPase-activating proteins (IQGAPs) and Forkhead Box M1(FOXM1) are two major proteins frequently studied in cancer therapies." (PMID 37202772, 2023). "As the 2010 Molecule of the Year, FOXM1 was considered a promising target for cancer therapy, yet the results of few studies have been clinically translated due to the insufficient understanding of the role of FOXM1 in tumours." (PMID 37620304, 2023). "While the selectivity of these drugs to specifically inhibit FOXM1 has yet to be determined, this set of FOXM1 inhibitors have compelling translational potential to one day be clinically tested in logical combination therapies against cancers driven by FOXM1." (PMID 37686402, 2023). "In this study, to internalize FOXM1 Apt to cancer cells, it was bound to the AuNPs-AFPA-Dox owning AS1411 as a targeting agent." (PMID 37736517, 2023). "FoxM1 upregulation in the majority of carcinomas is involved in tumor malignancy and the poor clinical prognosis by stimulating metastasis." (PMID 37968723, 2023). "Essentially, FoxM1 overexpression in CCA limited CD8+ T killing to promote cancer cell migration and defense against immunotherapeutic efficiency." (PMID 36301031, 2022). "Although the molecular mechanisms of FOXM1 on improving BC progression are poorly understood, there is the strong possibility that FOXM1 will be a promising therapeutic target for cancer treatment." (PMID 35481418, 2022). "Expression levels of FOXM1 have been reported to correlate with cancer progression, lymph node and liver metastases, and high TNM staging." (PMID 35864528, 2022). "Regenerative Aundiff induced expression of FOXM1, a cell cycle regulator with roles in tissue regeneration, cancer development and senescence." (PMID 35523793, 2022). "FOXM1 is known to promote invasion, angiogenesis, and progression of various cancer cells through induction of matrix metalloproteinase genes." (PMID 35978634, 2022). "In 2006, researchers found that TST downregulates the protein expression and transcriptional activity of the oncogenic transcription factor FOXM1 in cancer cells." (PMID 35859150, 2022). "We explored the expression profiles and the prognostic value of FOXM1 in pan-cancer across The Cancer Genome Atlas (TCGA)." (PMID 36435510, 2022). "FOXM1 is upregulated in several types of cancer, and there is increasing evidence that FOXM1 is actively involved in tumor progression." (PMID 35141332, 2022). "In turn FOXM1 in the nucleus recruits β-catenin to Wnt target-genes representing an additional mechanism for controlling canonical Wnt signaling and cancer cell proliferation." (PMID 35241126, 2022). "Subsequently, we investigated the expression of FOXM1 in different cancer cell lines to determine the universality and importance of FOXM1 expression." (PMID 36171633, 2022). "Forkhead box protein M1 (FOXM1) is a transcription factor of the Forkhead box (Fox) protein superfamily which shows overexpression in many different cancer types and is a regulator of cancer cell division, aggressiveness and metastasis." (PMID 34907642, 2022). "FOXM1 as a key proliferation-related transcription factor, will also play a vital role in cancer treatment." (PMID 36171633, 2022). "FOXM1 interacts with DEPDC1, which causes cancer in OSCC cells, according to these fundamental in vitro data." (PMID 36072787, 2022). "FOXM1 has been reported to promote β-catenin nuclear localization, thus activating Wnt signaling pathway and playing a tumor-promoting role in cancer." (PMID 35799265, 2022). "The results showed that intracellular paclitaxel concentrations were significantly increased following FOXM1 downregulation by both shRNA and Siomycin A, indicating the potential of Siomycin A in sensitizing chemo-resistant cancer cells to paclitaxel." (PMID 35141332, 2022).
cancer (continued). "The FOXM1 promoter contains CTCF binding site, and CTCF transcriptionally activates FOXM1 in cancer." (PMID 35378133, 2022). "Its degradation effect on FOXM1 was detected by Western blotting, qPCR, and we verified its effect on the behavior of cancer cells by flow cytometry, scratch assay, and Transwell in vitro." (PMID 36171633, 2022). "Forkhead box M1 (FOXM1) functioned as an oncogene in cancers and can be regulated by multiple microRNAs in mang maliganancies." (PMID 36506538, 2022). "Overexpression of FOXM1 can promote cancer cell migration and invasion and establish a premetastatic niche." (PMID 36591565, 2022). "FOXM1 is a potent oncogenic transcription factor essential for cancer initiation, progression, and drug resistance." (PMID 35680842, 2022). "The study also found that circ-ARAP2 influenced the endothelial–mesenchymal transition (EMT) and cancer stem cells differently by regulating miR-761/FOXM1." (PMID 35842667, 2022). "The transcription factor forkhead box M1 (FOXM1) is a well‐known proto‐oncogene that plays a significant role in the pathogenesis of various human cancers." (PMID 35656815, 2022). "The FOXM1-regulatory network is a critical predictor of poor prognosis in 18,000 cancer cases across 39 human malignancies." (PMID 36591565, 2022). "The forkhead box protein M1 (FOXM1) is a transcription factor which is evolutionarily conserved and involved in regulating cancer development and progression in various human malignancies." (PMID 36591473, 2022). "This lncRNA isoform is co-expressed with FOXM1-202, the canonical FOXM1 isoform commonly overexpressed during mitosis and in cancer progression." (PMID 36287120, 2022). "DEAD-box helicase 3 X-linked (DDX3) is a human RNA helicase that directly regulates m6A demethylase ALKBH5, thereby reducing m6A methylation of cancer stem cell transcription factor fork head box protein M1 (FOXM1) and Nanog, leading to chemoresistance." (PMID 36249071, 2022). "FOXM1 is a crucial mediator in transduction of signals to downstream effectors in human cancer to influence cancer‐related processes, such as proliferation, migration, invasion, angiogenesis and EMT." (PMID 35313071, 2022). "The upregulation of TF SIM2 stimulates the activity of downstream oncogene FOXM1 to construct an appropriate microenvironment for cancer cell metastasis through the secretion of exosomes from the malfunction of metabolism." (PMID 35164166, 2022). "It was further reported to regulate the cell cycle via deubiquitinated FOXM1, which is suggested to be one of the master regulators in cancers." (PMID 35884607, 2022). "During tumor development, myriad oncogenic pathways such as DVL3/Wnt/β-catenin, AKT/ERK/FOXM1, and mTOR/p70S6K signals etc. are constitutively activated in cancer cells." (PMID 35743298, 2022). "Upregulation or activation of FOXM1 in cancer plays a key role in numerous phenotypes including cell proliferation, CS, invasion, metastasis, and angiogenesis." (PMID 35365182, 2022). "FOXM1 is an oncogenic transcription factor which is elevated in several types of cancers, while its expression level in normal tissues is low." (PMID 35680842, 2022). "Together these data indicated that FIP-1 peptide binds to FOXM1 and significantly inhibits the viability of cancer cells as an antagonist of FOXM1." (PMID 36171633, 2022). "The results showed that the high expression of FOXM1 was significantly correlated with the poor prognosis of cancer patients." (PMID 36171633, 2022). "Recent studies have demonstrated that FOXM1 is upregulated and correlated with poor prognosis in a majority of cancers." (PMID 36435510, 2022). "fused a CPP‐R9 with a domain of FOXM1 and expressed the chimeric structure in bacteria successfully, demonstrating that the complex R9‐FOXM1 can inhibit the tumorigenic ability of cancer cells and tumour growth in nude mouse xenograft tumour models." (PMID 35593206, 2022).
cancer (continued). "As a well-known oncogenic transcriptional factor, FOXM1 is involved in tumorigenesis and progression in cancers." (PMID 35680842, 2022). "A recently developed FOXM1 inhibitor reduced β-catenin abundance and activity in different cancer cell lines and attenuated tumor growth in mouse xenograft models." (PMID 35053606, 2022). "Combined therapy with a FOXM1 inhibitor and anti‐4‐1BB antibody synergistically enhances cancer immunotherapy of immune‐resistant lung tumors." (PMID 35975458, 2022). "The master control gene FOXM1 codifies for a proliferation-specific transcription factor that plays a critical role in cell cycle progression and initiation of cancer development." (PMID 35053606, 2022). "The Forkhead box M1 (FoxM1) is one of the most frequently overexpressed transcription factors in many malignant tumors." (PMID 35884976, 2022). "Circ-FOXM1 (hsa_circ_0025033) is a newly recognized cancer-related circRNA located at chr12: 2966846–2983691 and derived from FOXM1 which has been report to be overexpressed in OS and promotes OS progression." (PMID 35799265, 2022). "It has been put forward that FOXM1 is a major factor of adverse prognosis in 18,000 cancer cases across 39 human malignancies, confirming the important role of FOXM1 in cancer." (PMID 35646056, 2022). "Regarding CRC biology, FOXM1 expression levels correlate with cancer progression, lymph node, liver metastasis, and high TNM stages." (PMID 36591565, 2022). "FDI-6, which is known for displacing FOXM1, is an important mitotic player that involved in cancer progression and drug resistance in MCF-7 cells and induces coordinated transcription down-regulation." (PMID 35688486, 2022). "Of note, several cancer associated genes such as CDH6, FOXM1, NAAA and CXCL10 were amplified and upregulated." (PMID 36352274, 2022). "Signaling activation relies on β-catenin nuclear localization, and FOXM1 promotes it in different cancer cells, which is highly correlated with tumor metastasis." (PMID 36530974, 2022). "The researchers found that the elevated ROS level triggered by erastin can stimulate Nedd4 expression by inducing Forkhead Box M1 (FOXM1), an essential regulator for oxidative stress and cancer cell survival." (PMID 36684424, 2022). "In order to clarify the relationship between FOXM1 and cancer in patients, we took liver hepatocellular carcinoma as an example to validate the differences in expression between normal tissues and tumors." (PMID 36171633, 2022). "Fork head box protein M1 (FOXM1) is overexpressed in various cancers, which is a necessary transcription factor for cell proliferation." (PMID 35938040, 2022). "To understand the role of FOXM1 in cancer progression and drug resistance, we used the FOXM1 inhibitor thiostrepton to determine the role of FOXM1 in cell death and colony formation." (PMID 35887129, 2022). "Many of these process require nuclear localization, particularly in cancer cells, including an interaction with transcription factor FOXM1." (PMID 35749404, 2022). "FOXM1 is a crucial transcription factor in cancer and maintains cancer hallmarks by regulating its target gene expression." (PMID 36357378, 2022). "FoxM1 expression was increased in intrahepatic CCA and associated with cancer cell growth and aggressiveness as well as poor prognostic consequences." (PMID 36301031, 2022). "Our findings highlight the immunoregulatory role of FOXM1 in cancer cells, suggesting the need for future investigations exploring FOXM1 as a prognostic biomarker, in addition to PD‐L1, for cancer immunotherapy." (PMID 35975458, 2022). "Then, we predicted and validated potential transcription factors (including E2F7, KLF5 and FOXM1) and therapeutic drugs (such as cyclophosphamide, vinblastine, and gefitinib) that target ferroptosis regulators in cancer." (PMID 34975326, 2022). "FOXM1 has an effect on the biological functions of various cancers through synergistic interactions or transcriptional regulation with CENPF and KIF20A." (PMID 35410446, 2022).
cancer (continued). "FOXM1 is a master transcription factor, regulating tumor cell proliferation, self-renewal and tumorigenesis in several human cancers." (PMID 36352274, 2022). "Given that circRNAs usually have roles in cancers through regulating their host genes, here we explored the relationship of circ-FOXM1 and its host gene FOXM1 in OS." (PMID 35799265, 2022). "Several studies have demonstrated that it plays a critical role in exacerbating metastatic activity, invasion, angiogenesis and cancer since FOXM1 is a crucial cell cycle proliferation regulator." (PMID 36072787, 2022). "FOXM1 is upregulated in most human tumors, such as GC, and plays a substantial role in regulating the proliferation, migration, and apoptosis of cancer cells." (PMID 36591473, 2022). "The function of FOXM1 in determining sensitivity of cancer cells to chemotherapy drugs has also been reported." (PMID 36291811, 2022). "FOXM1, a transcription factor gene, is highly expressed in cancer and is indispensable for the self-renewal and tumorigenesis of GSCs." (PMID 35628623, 2022). "Other members of the FOX family of TFs such as FOXA1, FOXM1, and FOXP1 are considered oncogenes and FOXC1 was implicated in cancer stemness through modulation of β-catenin signaling." (PMID 35349489, 2022). "In the present study, we evaluated the role of FOXM1 expression on signaling pathways, cancer stem cell marker status, and survival outcome in HCC patients." (PMID 35955438, 2022). "FOXM1 is highly expressed in several cancer types, such as GC, colorectal cancer, liver cancer, lung cancer, prostate cancer, and breast cancer." (PMID 36291811, 2022). "Decreased expression FOXO3 and increased expression of FOXM1, which contribute to increased chemoresistance in cancer has been reversed in co-treatments (5FU+UroA or 5FU+UAS03) suggesting potential translational applications." (PMID 35910798, 2022). "For instance, the overexpression of the FOXM1 gene has been detected in multiple cancer types, which reveals its oncogenic potential." (PMID 36555288, 2022). "The transcription factor FOXM1 is an established master regulator of tumorigenesis across several human cancers and was exclusively amplified in patients with EOBRCA." (PMID 36352274, 2022). "Kyoto Encyclopedia of Genes and Genomes (KEGG) and Gene Ontology (GO) pathways enrichment was analyzed to investigate the biological significance of FOXM1 expression in various cancers." (PMID 36435510, 2022). "Pan-cancer analysis showed that the FOXM1 expression in cancer was related to genomic instability and poor prognosis." (PMID 36555288, 2022). "Based on this, we analyzed the impact of differential expression of FOXM1 on the prognosis of cancer patients." (PMID 36171633, 2022). "FOXM1 is an oncogene and maintains cancer features by transactivating genes with tumor promotion potential." (PMID 35538067, 2022). "What is most attractive to us about FOXM1 is that it has been reported to overexpress in a wide range of cancers and contribute to all hallmarks of cancer." (PMID 35392496, 2022). "BUB1B also showed a highly significant positive correlation with FOXM1 in all the TCGA cancer types." (PMID 35847923, 2022). "Recent research has demonstrated that FOXM1 is overexpressed in most cancers, such as bladder cancer and cholangiocarcinoma, and related to poor prognosis." (PMID 36435510, 2022). "In terms of PFS, forest plot revealed that the hazard ratios for FOXM1 were significant for 18 cancer types." (PMID 36435510, 2022). "Interest in FOXM1 as a target for cancer therapy led to identification of novel compounds that directly inhibit FOXM1, including the antibiotic thiostrepton." (PMID 35523793, 2022). "It is also known that FOXM1 strongly correlates with cancer stem cell features and EMT characteristics." (PMID 35053606, 2022). "FOXM1 activity has been found to boost all hallmarks of cancer, including enhanced cell proliferation, genome instability, angiogenesis and suppressed cell senescence." (PMID 34907642, 2022).